RAF1 (Raf-1 proto-oncogene, serine/threonine kinase)
Diseases named in the same sentence as RAF1 in open-access papers (continued):
Sharing a sentence is not in itself a finding about the gene and the disease.
RASopathy (43 papers, 2015 to 2025). Developmental syndromes caused by germline mutations (or in rare cases by somatic mosaicism) in genes that alter the Ras subfamily and mitogen-activated protein kinases that control signal transduction. "Beyond cancer, numerous mutations in the RAF1 gene have been identified in Noonan Syndrome and other RASopathies, a spectrum of developmental syndromes caused by germline mutations in components of the RAS/MAP kinase pathway." (PMID 40890113, 2025). "More than 38% cases (12 cases) had variants in PTPN11, 5 had variants in SOS1 and RAF1 each, making these three the most common genes leading to RASopathy disorders." (PMID 41292581, 2025). "Due to the suggestive phenotype for NS, molecular genetic testing for RASopathies was performed in a center abroad and revealed the presence of RAF-1 mutation." (PMID 35950157, 2022). "Due to suggestive phenotype for NS molecular genetic testing for RASopathies was performed in a center abroad, establishing the presence of RAF-1 mutation." (PMID 35950157, 2022). "RAS then signals to numerous downstream effector pathways via serine/threonine kinase RAF (ARAF, BRAF and CRAF/RAF1), which, when dysregulated in the germline, causes RASopathies." (PMID 35103797, 2022). "Among these are three RASopathy genes (RAF1, RIT1 and PTPN11), which have been shown to cause isolated LVH in some patients, but have only been comprehensively evaluated in a small number of studies." (PMID 33673806, 2021). "In 15/16 cases, the RASopathy gene variant was the only LP/P variant identified, in one case two LP variants were seen; (RAF1 and TNNT2)." (PMID 33673806, 2021). "We find that mice harboring a mutation in Raf1 show moderate increases in the number of two subsets of glial cells, which is also observed in a number of other RASopathy brain samples." (PMID 31017896, 2019). "Indeed, the tool compound U0126, which inhibits MEK in part due to its ability to chelate copper, is effective in reversing RASopathy phenotypes in iPSCs derived from patients with RAF1-associated NS and in BRAF- and MEK-associated CFC." (PMID 35178568, 2022). "Similarly, hypertrophic cardiomyopathy occurs in patients with RASopathy, particularly those with germline RAF1 and RIT1 mutations as well as in mouse models carrying mutations in these genes." (PMID 32990679, 2020). "Our work indicates RAF1 as the priority candidate causative gene for wg-2 and provides a new animal model to study an important signaling pathway implicated in limb development, as well as RASopathies." (PMID 31075853, 2019). "NS is the most common type of RASopathy, and is a rare genetically heterogeneous autosomal dominant disorder caused by mutations in either the PTPN11, SOS 1, KRAS, BRAF or RAF1 genes." (PMID 37106005, 2023). "Similar to pathogenic and likely pathogenic variants, heterozygous VOUS were identified in RASopathy genes (SOS1, SOS2, and RAF1), inherited from unaffected parents." (PMID 36959127, 2023). "On the other hand, in patients with other RASopathies, multifocal atrial tachycardia (MAT) seems to be associated specifically with RAF1 mutations." (PMID 33718303, 2021). "Phosphorylation of the RASopathy proteins RAF1, PTPN11, and BRAF is altered in NS and NSML due to mutations in their corresponding genes, whereas RASA1 altered phosphorylation is associated to mutant SHP2 models and not to its own mutation." (PMID 34229750, 2021). "Found in perhaps 1:1000 new births, RASopathies are associated with variants in genes encoding multiple RAS pathway components including KRAS, NRAS, BRAF, RAF1, and SHP2." (PMID 33855281, 2021). "Regarding diagnosis of other RASopathies patients with multiple lentigines, genetic tests were needed to exclude candidate RASopathy genes, such as PTPN11 and RAF1, mutations." (PMID 32357851, 2020).
RASopathy (continued). "RAF1 encodes a protein integral to the Ras/Raf/MAPK signaling pathway controlling cellular proliferation, and notably, human RASopathies are developmental syndromes caused by germline mutations in genes of this pathway." (PMID 31075853, 2019). "Errors in RAF1 or other members of the Ras/MAPK pathway are termed RASopathies in humans and are phenotypically similar to wg-2 in that multiple developmental systems are affected, and some clinical features of these disorders are shared." (PMID 31075853, 2019). "In addition, variants were identified in a wide range of other RASopathy-associated genes, including LZTR1, BRAF, SOS1, and RAF1, underscoring the necessity of broad genetic testing approaches such as WES in cases with overlapping phenotypes." (PMID 41292581, 2025). "Estimations of Sanger sequencing prices were performed for five genes most commonly associated with RASopathies (BRAF, NF1, PTPN11, RAF1, and SOS1), and three genes, TCOF1, CHD7, and NIBPL most commonly associated with Treacher Collins, CHARGE, and Cornelia de Lange syndromes, respectively." (PMID 37815686, 2024). "RASopathies represent a family of mostly autosomal dominant diseases that are caused by missense variants in the rat sarcoma viral oncogene/mitogen activated protein kinase (RAS/MAPK) pathway including KRAS, NRAS, BRAF, RAF1, and SHP2." (PMID 33855281, 2021). "Previous work has elucidated specific behaviors impacted by RAF1 and NF1 RASopathy mutations." (PMID 34222248, 2021). "Though the overall activity of this pathway was not assessed in wg-2, it is likely that absent RAF1 results in overall loss of function, unlike a typical RASopathy." (PMID 31075853, 2019). "In addition, it has been confirmed by molecular diagnosis that AVCD is a part of the phenotypic spectrum of CHDs found in patients with RASopathies, in particular those caused by PTPN11 and RAF1 gene mutations, as the third most common CHD." (PMID 27990414, 2016). "For the RASopathy genes, no protein structures were available for RAF1, MAP2K2, or SHOC2 (9 total variants)." (PMID 25802880, 2015). "A plausible hypothesis is that complete absence of chicken RAF1 results in overall loss of function of the pathway, unlike a typical RASopathy." (PMID 31075853, 2019). "For example, RASopathies, such asNoonan syndrome, Neurofibromatosis 1 and Leopard syndrome, are a subtype ofdevelopmental diseases characterized by mutations in genes encoding for components ofthe Ras/MAPK pathway (NF1, PTPN1, SOS1, RAF1,KRAS, NRAS, SHOC2, CBL)." (PMID 29719609, 2018). "Our reported proportion may be an underestimate of the true prevalence of RASopathy findings, as earlier versions of the HCM and cardiomyopathy panels utilized in this study did not include the most common of the RASopathy genes associated with left ventricular hypertrophy (PTPN11, RAF1, RIT1)." (PMID 33673806, 2021). "BRAF, CBL, NF1, PTPN11, RAF1, SOS1 and SOS2 contain at least 20 phosphosites each, and they account for 326 of the phosphosites identified in RASopathy proteins (61% of the total)." (PMID 34229750, 2021). "In this context, ERAS adds up to the list of genes whose mutation can lead to overgrowth syndromes (as AKT, PIK3CA, PTEN) or RASopathies (as H-RAS, RASA1, NF1 and RAF1, among others)." (PMID 34771750, 2021). "Expressing human RASopathy isoforms of KRAS, HRAS, RAF1, BRAF, and PTPN11 in Drosophila, we report important differences between disease isoforms including distinct signaling pathways and drug responses." (PMID 33855281, 2021). "The mean (±SD) number of genes per panel was 33±25, including 8±0.3 sarcomere genes, 4±2 storage cardiomyopathy, and RASopathy genes (LAMP2, PRKAG2, TTR, GLA, PTPN11, RIT1, and RAF1) and 22±23 other genes (range, 0–75)." (PMID 30681346, 2019).
RASopathy (continued). "Immunoblotting results show that dysregulation on several phosphoproteins account for more than one RASopathy, including ERK1/2 (Thr202/185 and Tyr204/187), AKT1 (Thr308 and Ser473), MEK1 (Thr292) and RAF1 (Ser259), which are the most co-occurring studied proteins along the syndromes." (PMID 34229750, 2021). "While we propose RAF1 insufficiency as a plausible genetic etiology for ACFS, it may not necessarily be classified as a RASopathy, which typically involve gain‐of‐function rather than loss‐of‐function mutations." (PMID 37066513, 2023). "RASopathies also include NF1 (OMIM code #162200) and LS (OMIM code #611431), caused, respectively, by inactivating mutations of NF1, which encode for a GTPase activating protein, and SPRED1, which is a negative mediator of RAS-mediated RAF 1 activation." (PMID 33718303, 2021). "It is noteworthy that RASopathies are not typically described as lethal, and we speculate that a complete knockout of RAF1, as in wg-2 and mouse models, could not be tolerated in humans." (PMID 31075853, 2019).
hepatocellular carcinoma (40 papers, 2012 to 2025). A malignant tumor that arises from hepatocytes. "High‐fidelity CRISPR/Cas12a dual‐crRNA screening identifies synergistic interactions of Raf1‐Pkm2 in the development of hepatocellular carcinoma." (PMID 39073026, 2024). "Correlation between Raf1 and Pkm2 expression and clinicopathological characteristics in hepatocellular carcinoma." (PMID 39073026, 2024). "Our results support and extend previous studies that indicate that RAF1 downregulation promotes the proliferation and migration of hepatocellular carcinoma cells." (PMID 35836300, 2022). "Knocking down RAF1 with doxycycline leads to enlargement of mouse hepatocellular carcinoma xenograft." (PMID 35836300, 2022). "RAF1 is a negative regulator of hepatocarcinogenesis; downregulating RAF1 promotes the proliferation of human hepatocellular carcinoma in xenografts and cell culture, and it promotes the proliferation of mouse hepatoma cells and hepatocarcinogenesis." (PMID 35836300, 2022). "Sorafenib is a Raf1 / Mek / Erk kinase inhibitor used to treat hepatocellular carcinoma, thyroid carcinoma, and renal carcinoma." (PMID 34604242, 2021). "Reactive species promote Raf-1 translocation within mitochondria, contributing to the onset of hepatocellular carcinoma." (PMID 32435643, 2020). "One of these multikinase inhibitors (MKIs), sorafenib, was originally intended to treat advanced renal cell carcinoma and hepatocellular carcinoma patients by blocking the serine threonine kinase RAF-1 in the RAF/MEK/ERK signalling cascade." (PMID 29304116, 2018). "Raf1 phosphorylation on serine 259 by Akt has also been shown in the HGF stimulated human hepatoma cell line Hep3B." (PMID 25905717, 2015). "Other experiments reported the activation of Ras-RAF-MEK-ERk stimulating the replication of Hepatitis C virus by downregulating the interferon-JAK-STAT pathway, while the Hepatitis B virus can regulate the RAF1 expression in HepG2.2.15 cell inducing hepatocellular carcinoma." (PMID 37910477, 2023). "In addition, CircAGFG1/miR-370-3p and CircCDR1/miR-1287 were reported to regulate the transcription of RAF1 in cervical cancer and hepatocellular carcinoma respectively." (PMID 38111008, 2023). "Studies have shown that LHBs activate the Src/PI3K/Akt signaling pathway through proximal stimulation of the PKCα/Raf1 signaling pathway, which could promote the tumorigenesis of hepatoma cells." (PMID 36193202, 2022). "Results from experiments in cervical, renal, non-small-cell lung, osteosarcoma, and hepatocellular cancer cells show that miR-497-5p regulates cell growth and proliferation and is associated with the MAPK pathway by targeting several involved genes such as RAF1, KDR/VGFR-2, and IGF1-R." (PMID 33374439, 2020). "Notably, a study on hepatocellular carcinoma (HCC) revealed a protective role of RAF1, demonstrating its downregulation in HCCs compared to normal hepatocytes." (PMID 40362553, 2025). "Therefore, FDA‐approved combinations of drugs that target both Raf1 and Pkm2, such as sorafenib and benserazide, may be promising for clinical liver cancer treatment, as confirmed by our combination treatment in multiple hepatocellular carcinoma cells." (PMID 39073026, 2024). "Hence, these results indicated that PID1 could accelerate Sorafenib-induced Raf-1 activation and facilitate the formation of Raf-1/BRAF heterodimerization, thereby blocking AKT activation via Raf-1-dependent pathway and leading to increased sensitivity of hepatoma cells to Sorafenib." (PMID 37117198, 2023). "In summary, CDK1, CCND1, RAF1, CDKN1B and BTRC were defined as top 5 hub target-genes, and the patients with hepatocellular cancer with high expression of CDK1 showed poor prognosis." (PMID 35836300, 2022). "In hepatocellular carcinoma, it was shown that DGKα is involved in the tumor progression by activation of the MAPK pathway via modulation of Raf-1 (C-Raf)." (PMID 36358678, 2022).
hepatocellular carcinoma (continued). "Sorafenib is the only drug currently approved for advanced Hepatocellular Carcinoma (HCC) and acts by blocking Vascular Endotelial Growth Factor Receptor 2 (VEGFR2), Platelet Derived Growth Factor Receptor (PDGFR), Raf-1, B-Raf and c-kit among others." (PMID 24902850, 2014). "RAF1 exerts dual roles in STAT3 activation; in hepatocellular carcinoma, RAF1 acts as a cell-autonomous tumor suppressor by negatively regulating STAT3 activation, while it has been described as a STAT3 activator in squamous cell carcinoma through its interaction with ROKα." (PMID 37020037, 2023). "Anti-VEGF treatment increases survival and is the standard-of-care for hepatocellular carcinoma (HCC), with sorafenib (VEGFR2, PDGFR, Raf1 inhibitor), lenvatinib (VEGFR, FGFR, c-Kit and RET inhibitor) and regorafenib (VEGFR2, Tie2 inhibitor) being common treatments." (PMID 33804681, 2021).
colorectal cancer (38 papers, 2012 to 2025). A primary or metastatic malignant neoplasm that affects the colon or rectum. "In this regard, the activation of BRAF, a proto-oncogene strongly linked to CD-associated colorectal cancer, has been shown to override RAF1 signalling and activate MEK1/272,73." (PMID 34075172, 2021). "In addition to KRAS mutation, genetic alterations in NRAS, HRAS, BRAF, and RAF1 were found in colorectal cancer samples analyzed in this study." (PMID 23700467, 2013). "The overexpressed siRS-7 activated the downstream oncogenes EGFR and RAF1 of miR-7 by inhibiting miR-7, which made colorectal cancer more aggressive." (PMID 39959665, 2025). "Previous research also revealed that miR-455 inhibited the aggressive behaviors of colorectal cancer cells by down-regulating RAF1, suggesting the potential therapeutic significance of miR-455/RAF1 signaling in the treatment of colorectal carcinoma." (PMID 39076089, 2024). "Little is known about the mechanistic role of RAF proteins and especially of RAF1 in colorectal cancer (CRC)." (PMID 37020037, 2023). "First, we demonstrated that complete ablation of RAF1 by CRISPR/cas9 genome engineering or RAF1 silencing with shRNA reduces the proliferation of human colorectal cancer cell lines and patient-derived organoids, respectively." (PMID 37020037, 2023). "In the present study, we investigated the role of RAF1 in colorectal cancer by using human 3D models as spheroids from CRC cell lines and patient-derived organoids." (PMID 37020037, 2023). "An in vitro model of colorectal cancer showed a decrease in miR-143 expression, whose target gene is, among others, the Raf1 oncogene." (PMID 35627259, 2022). "For instance, IGF2BP2 promotes colorectal cancer cell proliferation and survival via disturbing RAF-1 degradation by miR-195." (PMID 36257938, 2022). "To further confirmed the association between H19, hnrnpA2B1 and Raf-1, we analyzed the expression of H19, hnrnpA2B1 and Raf-1 in the primary colorectal cancer tissues and demonstrated the expression of H19 is positive correlated with Raf-1." (PMID 32698890, 2020). "We found that LSA induced RAF1 phosphorylation on Serine 338 within minutes in human colorectal carcinoma HCT-116, ovarian carcinoma OVCAR-8, and Burkitt’s lymphoma CA46 cell lines." (PMID 26058013, 2015). "Finally, RAF1 is integral to the MAPK/ERK pathway implicated in cell growth and colorectal cancer." (PMID 39769296, 2024). "In colorectal cancer, one study reported that both PHLPP1 and PhLPP2 dephosphorylated RAF1, thereby inhibiting colorectal cancer proliferation." (PMID 37576883, 2023). "UDCA is cytoprotective against secondary BAs such as DCA and has been previously shown to be able to inhibit DCA-induced activation of the EGFR/Raf-1/ERK signaling pathway in HCT-116 cells and in an azoxymethane mouse model for colorectal cancer." (PMID 29241453, 2017). "Among these miRNAs, miR-497 is down-regulated in breast, gastric, and colorectal cancer and promotes cell proliferation and invasion by up-regulating raf-1/Ccnd1, EIF4E, and insulin growth factor 1 receptor in breast, gastric, and colorectal cancer." (PMID 27531900, 2016). "Furthermore, knockdown of STOML2 downregulated phosphorylation of RAF1, MEK1/2, and ERK1/2 on the MAPK signaling pathway, indicating common pathway activated by STOML2 and PHB in colorectal cancer proliferation." (PMID 34781982, 2021). "Based on previous findings and published validated targets for miR-7 such as EGFR, PAK1, RAF1, IRS1/2 and CD98, it is fair to hypothesize that this miR may be involved in regulating intracellular signaling, growth and differentiation of colorectal cancers." (PMID 22529906, 2012).
viral infection (38 papers, 2012 to 2025). "RAF1 is a key player in growth factor receptor signaling, which has been linked to multiple viral infections, including human cytomegalovirus (HCMV) infection." (PMID 39902964, 2025). "We find that RAF1 is phosphorylated by AMP-activated protein kinase, and that inhibition of RAF1 negatively impacts viral infection." (PMID 39902964, 2025). "Sorafenib has been identified as RAF1 and BRaf protein kinase inhibitor and has been reported to inhibit viral infectivity by downregulating ERK/MAPK signaling pathways during viral infection." (PMID 34067609, 2021). "Together, these data indicate that inhibition of the RAF1 pathway can inhibit viral infection and spread without impacting cell viability." (PMID 39902964, 2025). "While all modes of targeting RAF1 suggested that it is important for HCMV infection, the differences in the magnitude of inhibition suggest that it can be beneficial to target gene expression in multiple ways to obtain a more accurate picture of the contributions to viral infection." (PMID 39902964, 2025).